CASP9 (caspase 9)
Diseases named in the same sentence as CASP9 in open-access papers (continued):
Sharing a sentence is not in itself a finding about the gene and the disease.
Hyperglycemia (11 papers, 2014 to 2022). An increased concentration of glucose in the blood. "In vivo, the results show that the expressions of cleaved caspase-3, cleaved caspase-9, and Bax/bcl-2 were obviously upregulated in the DM group compared with the normal group, which indicates that hyperglycemia induced severe apoptosis." (PMID 35890121, 2022). "The results showed that hyperglycemia induced the upregulation of caspase-3 and caspase-9 (F = 23.95, p < 0.05; F = 19.37, p < 0.05), downregulation of Nrf2 and HO-1 (F = 21.58, p < 0.05; F = 23.72, p < 0.05)." (PMID 32792939, 2020). "High levels of caspase 9 expression suggest the initiation of apoptosis in the glomerulus and renal tubules in response to hyperglycaemia-induced oxidative stress." (PMID 31412679, 2019). "Hyperglycemia and OS can trigger an increase in Bax levels, which activates the apoptosis-signaling pathway, including the cleavage of both caspase-3 and caspase-9." (PMID 30373106, 2018). "Western blot analysis was performed to evaluate the induction of apoptosis by hyperglycemia, including the death receptor and mitochondrial pathways characterized by the expression of caspase-8 and caspase-9, respectively, which were evaluated as well as the downstream executor caspase-3." (PMID 33584279, 2020). "We showed that prolonged hyperglycemia and its related intracellular stresses induced profound morphological and functional mitochondrial damage as well as mitochondria-dependent apoptosis through the intrinsic cell death pathway involving BCL-2 and caspase-9 activation." (PMID 34445504, 2021). "In our experiment, HG or hyperglycemia induced cardiomyocyte apoptosis, while PARP-1 inhibition or deletion could significantly reduce the number of apoptotic cells, with downregulation of cleaved caspase-3 and caspase-9." (PMID 27027354, 2016).
acute myeloid leukemia (10 papers, 2016 to 2024). Acute myeloid leukemia (AML) is a group of neoplasms arising from precursor cells committed to the myeloid cell-line differentiation. "Additionally, Nusrat Khan and his co-workers developed a CD33 targeting vector to express an inducible caspase-9 suicide gene in acute myeloid leukaemia therapy." (PMID 32272948, 2020). "Emodin induces apoptosis and growth inhibition of AML (acute myeloid leukemia) cells through the activation of caspase-9, caspase-3, PARP (poly-ADP-ribose-polymerase), cleavage and decrease of the expression of antiapoptotic factors such as Bcl-2 (B-cell lymphoma 2)." (PMID 35011730, 2022). "In THP-1 acute myeloid leukaemia cells, there was a significant decrease in the expression of BCL2, BCLX, and BAD genes and proteins; with a significant increase in TNFR1/TNFRSF1A, CASP-9, and CASP-3 gene expression, when compared to the vehicle control (P ≤ 0.05)." (PMID 35614109, 2022). "Furthermore, the non-apoptotic functions of caspase-9 have been explored in acute myeloid leukemia, demonstrating that activation of caspase-9 activity promotes granulocytic differentiation in leukemic cells." (PMID 39625520, 2024). "In acute myeloid leukemia (AML) cells, NOB induces cell cycle arrest at the G0/G1 phase through downregulating ERK signaling pathway, increases cell apoptosis through activation of caspase-3, caspase-9, and caspase-8, and upregulates of MAPK signaling pathway in HL-60 cell line." (PMID 27761146, 2016).
endometrial cancer (10 papers, 2014 to 2025). Primary or metastatic malignant neoplasm involving the endometrium (mucous membrane that lines the endometrial cavity). "Mechanistically, cisplatin induced the MLH1/c-Abl apoptosis signaling pathway in ADV-MLH1-infected endometrial carcinoma cells, and these effects involved c-Abl, caspase-9, caspase-3 and PARP." (PMID 30594176, 2018). "Fenretinide decreased human endometrial cancer Ishikawa cell viability by inducing apoptosis as demonstrated by an increase in cell death markers (cleaved caspase-9 and cleaved PARP)." (PMID 25340777, 2014). "Additionally, a higher caspase-9 activity, compared to the control, was observed in the endometrial cancer cell cultures exposed to cisplatin (2.5 μM of the drug = 133.58%; p = 0.0000; 5 μM = 140.55%; p = 0.0000; 10 μM = 147.09%; p = 0.0000)." (PMID 32531934, 2020). "The downregulation of MMP23B (Matrix Metalloproteinase 23B) reduced the cell viability of endometrial cancer cells, upregulated the expression levels of CASP3 (Caspase-3), CASP8 (Caspase-8) and CASP9 (Caspase-9) in cells, and inhibited cell migration and invasion." (PMID 38782818, 2024). "Therefore, we examined the potential participation of c-Abl, B-cell lymphoma-2 (bcl-2), caspase-9, caspase-3 and PARP in the cisplatin-induced MLH1/c-Abl apoptosis signaling pathway in endometrial carcinoma cells via Western blot analysis." (PMID 30594176, 2018). "Atovaquone inhibited the viability of human ovarian and endometrial cancer cell lines of human (OVCAR-3, SKOV-3 and ECC-1) and murine (ID8) origin by inducing apoptosis as indicated by an increase in annexin V on the cell surface, cleaved caspase 3 and cleaved caspase 9 and a decrease in Bcl-2." (PMID 35565426, 2022).
nasopharyngeal carcinoma (10 papers, 2010 to 2025). A carcinoma arising from the nasopharyngeal epithelium. "This type-II RIP has been reported to induce apoptosis by activation of both caspase-8 and caspase-9 regulated pathways in nasopharyngeal carcinoma cells." (PMID 22957017, 2012). "For example, Epithelial Membrane Protein 1 (EMP1) is expressed in high levels in human cancers and was shown in vitro to reduce cell migration and invasion, and was also shown to increase apoptosis and caspase-9 expression in carcinoma of the nasopharynx, stomach, breast and prostate." (PMID 35054064, 2022). "Consequently, it leads to cytochrome c release and sequential activation of caspase-9 and caspase-3 in the nasopharyngeal carcinoma-TW 076 cells." (PMID 32454872, 2020). "It has also been shown that AE can induce apoptosis in nasopharyngeal carcinoma cell lines (NPC-TW 039 and NPC-TW 076 cells) by regulating caspase activities, including caspase-3, caspase-8, and caspase-9." (PMID 32190086, 2020). "In nasopharyngeal carcinoma, RBMS3 activates caspase-9 and PARP to promote tumor cell apoptosis in a mitochondria-dependent manner, repressing the microvessels formation via downregulating MMP2 and β-catenin." (PMID 37968257, 2023). "In contrast, in carcinoma of the nasopharynx, stomach, breast, urothelium, and prostate, EMP1 reduces cell migration and invasion and increases apoptosis and caspase-9 expression." (PMID 33747919, 2021).
acute lymphoblastic leukemia (9 papers, 2014 to 2025). Leukemia with an acute onset, characterized by the presence of lymphoblasts in the bone marrow and the peripheral blood. "In addition, acute lymphoblastic leukemia cell apoptosis increased due to the loss of mitochondrial membrane potential and up-regulation of cleaved Caspase 3/7, Caspase 9, and poly ADP ribose polymerase (PARP)." (PMID 28654902, 2017). "Resveratrol induces apoptosis in acute lymphoblastic leukaemia (ALL) cells by involving a mitochondria/Caspase 9-specific pathway to activate Caspase cascade, working independently of the CD95-signaling." (PMID 36672729, 2023). "Studies have shown that resveratrol induces apoptosis in different acute lymphoblastic leukemia cells by depolarizing mitochondrial membranes and activating caspase-9." (PMID 32104190, 2020). "In hematologic malignancies, resveratrol induces mitochondrial apoptosis in acute lymphoblastic leukemia (ALL) cells via caspase-9 activation and p16/INK4A-mediated S-phase arrest, independent of CD95 signaling." (PMID 41291133, 2025). "In Jurkat acute lymphoid leukaemia cells, there was a significant increase in the expression of BAD, BAX, and CYT c genes and proteins, as well as CASP-9 and CASP-3 genes when compared to the vehicle control (P ≤ 0.05)." (PMID 35614109, 2022). "Interestingly, the mitochondrial membrane depolarization and the Casp-9 activation were involved in the RSV-mediated cell death of several Acute Lymphoblastic Leukemia (ALL) cell lines." (PMID 24658441, 2014). "Acute lymphoblastic-leukemia (ALL) cells showed comparable triptolide mediated XIAP suppression (10–100 nM, 24–48 h), which was correlated with a reduction in release of cytochrome c mediated by caspase-9 and Mcl1 via the mitochondrial apoptotic mechanism." (PMID 38293343, 2024).
Parkinson disease (9 papers, 2015 to 2025). A progressive degenerative disorder of the central nervous system characterized by loss of dopamine producing neurons in the substantia nigra and the presence of Lewy bodies in the substantia nigra and locus coeruleus. "Furthermore, pre-treatment of SH-SY5Y and SK-N-SH cells with KYNA was shown to reduce the 1-methyl-4-phenylpyridinium-induced neuronal cell death through the attenuation of caspase-9/-3 activities in an in vitro model of Parkinson’s disease." (PMID 39153038, 2024). "Moreover, in a Parkinson’s disease mouse model, decreased intraneuronal a synuclein aggregation was reported following miR-29c induced inhibition of pro-inflammatory cytokines production and caspase-3 and caspase-9 expression." (PMID 38230736, 2024). "Oxidative stress in Parkinson’s enhances the aggregation of SNCA enhancing ER stress which in turn increases caspase-3, caspase-9, and caspase-12 activity." (PMID 40636521, 2025).
atherosclerosis (8 papers, 2016 to 2024). A disease characterized by the build-up of fatty material and calcium deposition in the arterial wall resulting in partial or complete occlusion of the arterial lumen. "Clinical reports suggest alterations in caspase-9 expression, activity or function may be associated with acute and chronic neurodegeneration, retinal neuropathy, slow-channel myasthenic syndrome, lumbar disc disease, cardiomyopathies, atherosclerosis and autoimmune disease." (PMID 34305609, 2021). "Apoptosis in atherosclerosis is well documented as an active programmed process of autonomous cellular dismantling including activation of apoptotic caspase-3, caspase-8, and caspase-9." (PMID 31871426, 2019). "In ApoE (-/-) mice with HFD-induced atherosclerosis, the elevated expression of pro-apoptosis factors caspase-3, caspase-9 and Bax and the decreased level of anti-apoptosis factor Bcl-2 were induced by miR-210 overexpression." (PMID 28536634, 2017). "Studies related to the inflammatory storm in atherosclerosis also indicated overexpression of inflammatory cytokines IL-17, IL-1β, and TNF-α, along with elevated expression of Caspase-3, Caspase-9, and Caspase-12." (PMID 39494338, 2024).
B-cell lymphoma (8 papers, 2013 to 2024). "The ivermectin–gemcitabine combination significantly increased the expression levels of B-cell lymphoma-associated X, caspase 3, and caspase 9 and decreased the levels of B-cell lymphoma-extra-large and B-cell lymphoma-2 compared to gemcitabine alone." (PMID 36091811, 2022). "Lastly, the expression levels of glyceraldehyde-3-phosphate dehydrogenase (GAPDH), cleaved caspase-9, cytochrome C (Cyt-C), B cell lymphoma/leukemia-2 (Bcl-2), B cell lymphoma/leukemia-2 associated X (Bax), AKT, p-AKT, PI3K, and p-PI3K were analyzed utilizing western blotting." (PMID 35414825, 2022). "Eugenol may have an apoptotic effect by reducing cyclooxygenase-2 (COX-2), B-cell lymphoma, and interleukin-1 beta production, and by increasing the activity of caspase-3 and caspase-9 caspase proteins." (PMID 37205310, 2023). "In contrast, the expression of caspase-9 in the HCS treated Ramos cells was not altered (data not shown), suggesting the HCS-induced apoptotic effect is mediated through different molecular mechanisms in HCC and B-cell lymphomas." (PMID 26062471, 2015).
esophageal cancer (8 papers, 2016 to 2025). A primary or metastatic malignant neoplasm involving the esophagus. "Flow cytometry data showed that the down-regulation of HuR could induce a G1 phase cell cycle block in esophageal cancer cells, and aggravate X-ray-induced apoptosis, indicated by the increases of apoptosis-related proteins Bax, caspase-3 and caspase-9." (PMID 35664798, 2022). "In contrast, in the present study, we observed a significant decrease in the level of Bcl-2 accompanied by increased levels of Bax, caspase-3, and caspase-9, indicating that pristimerin is able to trigger intrinsic apoptosis thereby inducing esophageal cancer cell death." (PMID 31218209, 2019). "In conclusion, our results demonstrate that SKF96365 inhibits tumor growth by inhibiting TRPC1 in esophageal cancer cells and inducing apoptosis (PARP, caspase-9, and BCL-2) and autophagy (LC3-A/B)." (PMID 39165489, 2024). "In summary, SKF96365 induces apoptosis (PARP, caspase-9, and BCL-2) and autophagy (LC3-A/B) by inhibiting TRPC1 in esophageal cancer cells, thereby inhibiting tumor growth." (PMID 39165489, 2024). "Furthermore, Western blotting revealed that ferrichrome significantly induced caspase-9 and PARP cleavage, suggesting that ferrichrome-induced apoptosis in esophageal cancer cells." (PMID 38545201, 2024). "Similarly, OCT1 was discovered to be directly regulated by STAT3 to reduce the expression of caspase 9, BAX, and BAD via ERK and AKT activation to boost proliferation and inhibit apoptosis in esophageal cancer cells." (PMID 26433389, 2016). "Bax, cleaved caspase-3, cleaved caspase-9, cytochrome C and cleaved PARP levels were increased after treatment with Rk3, whereas Bad and Bcl-2 levels were reduced in a dose-dependent manner in both Eca109 and KYSE150 cells, indicating that Rk3 activated apoptosis in esophageal cancer cells." (PMID 31091245, 2019).
Cerebral ischemia (7 papers, 2004 to 2023). Restriction of arterial blood supply to the brain associated with insufficient oxygenation to support the metabolic requirements of the tissue. "Of note, cerebral ischemia triggers both intrinsic pathway that originates from mitochondrial crash associated stimulation of caspase-9 and the extrinsic pathway that derives from death receptors activation and subsequent stimulation of caspase-8." (PMID 28428752, 2017). "We have previously shown that Pen1-XBIR3 inhibits caspase-9 dependent cell death using primary hippocampal neuron cultures, and that Pen1-XBIR3 delivery to the CNS blocks caspase-9 in an in vivo model of cerebral ischemia." (PMID 23217200, 2012). "In line with our data, others have observed activation of both caspase-9 and caspase-8 following hypoxic stress in animal models of brain ischemia." (PMID 15613236, 2004). "In our study, the results demonstrated that the number of TUNEL-positive cells, Bax, cleaved caspase-3, cleaved caspase-9, PARP, IL-1β, IL-6 and TNF-α protein expression were enhanced after cerebral ischemia‒reperfusion injury, while antiapoptotic Bcl-2 protein expression was decreased." (PMID 37248543, 2023).
lung adenocarcinoma (7 papers, 2020 to 2025). A carcinoma that arises from the lung and is characterized by the presence of malignant glandular epithelial cells. "Campesterol induced cell apoptosis through the mitochondrial pathway; it decreases the expression of BCL-2 and BCL-xL and increased the expression of BAX, BAD, BAK, and activating caspase 3 and caspase 9 in human lung adenocarcinoma (A549) cells." (PMID 33802602, 2021). "and induced cytotoxic potential against A549 lung adenocarcinoma cell lines by inducing apoptosis through enhancing the activity of caspase-3 and caspase-9 and inhibiting the synthesis of Bcl-2 protein as well as cytochrome c release from mitochondria." (PMID 33808594, 2021). "Caspase-9 inhibitor and nec-1 were able to prevent tumor cells from apoptosis and necroptosis, respectively, in the EGFR-mutant lung adenocarcinoma cells." (PMID 34367939, 2021). "In addition, in this context, it has been reported that in lung adenocarcinoma cells, OLE increased the Bax/Bcl-2 ratio and activation of caspase-9 and -3, leading to cell apoptosis." (PMID 35684123, 2022).
medulloblastoma (7 papers, 2014 to 2023). A malignant, invasive embryonal neoplasm arising from the cerebellum. "The knockdown of lncRNA CRNDE induces apoptosis via promoting the activity of caspase-3 in medulloblastoma cells Cleaved-caspase-3, caspase-9, and Bax elevation, and bcl-2 reduction are the results of HOTAIR downregulation in medulloblastoma cells." (PMID 35111757, 2021). "JEV, DENV2, and West Nile virus (WNV) infections induce caspase-9 activation and cytochrome c release in human medulloblastoma cells." (PMID 34834918, 2021). "First of all, across 17 analyses, AXIN2 (Median rank 178, P < 0.05) was highly expressed in various tumors compared to normal tissue, while CASP9 (Median rank 28, P < 0.05) showed higher expression only in medulloblastoma in the Oncomine." (PMID 31681739, 2019). "According to 17 analyses, AXIN was highly expressed in various tumors compared to normal tissue, while CASP9 was highly expressed only in medulloblastoma across two analyses." (PMID 31681739, 2019). "BAX and SMAC were most highly expressed in Group 4 medulloblastoma cell lines compared with the SHH and Group 3 subgroups, while pro-caspase 9 was more highly expressed in the SHH subgroup, compared to Group 4 cell lines." (PMID 37898609, 2023).
thyroid cancer (7 papers, 2019 to 2025). "In addition, the loss of CASP9 signaling can lead to tumor immune escape and tumor recurrence by up-regulating PD-L1, which also provides new insights for immunotherapy of thyroid cancer." (PMID 36675746, 2022). "Protein expression of three PRGs was then determined, where CASP6 and IL18 were increased in thyroid cancer tissues, while CASP9 was down-regulated, which was also consistent with the bioassay results." (PMID 36675746, 2022). "AMPs have been shown to promote the apoptosis of tumor cells, and a melittin derivative (TT-1) was shown to stimulate caspase-3, caspase-9, and Bax expression and promote the apoptosis of human thyroid cancer cells (TT) following TT-1 treatment." (PMID 30736473, 2019). "Similarly, alantolactone induces caspase-9 and caspase-3 cleavage via the mitochondrial intrinsic pathway, inhibiting proliferation and inducing pyroptosis in thyroid cancer cells." (PMID 41226386, 2025). "In this study, the expression of Caspase-3 and Caspase-9 in miR- 195 mimic + TERT group cells was significantly increased, which may indicate that over-expressedmiR-195-5p mimics effectively increased apoptotic factors, causing thyroid cancer cells to be rapidly inhibited." (PMID 34482792, 2021).
Cognitive impairment (6 papers, 2016 to 2026). Abnormal cognition is characterized by deficits in thinking, reasoning, or remembering. "In the present study, inosine treatment decreased Bax, Caspase-9, and Caspase-3 mRNA levels and upregulated Bcl-2 expression in HT-22 cells, thereby alleviating D-gal-induced cognitive impairment in mice." (PMID 41596947, 2026). "The correlation between caspase-9 blood protein levels and cognitive impairment suggest systemic alterations in apoptosis regulation may be implicated in the progression of neurodegenerative disease." (PMID 34305609, 2021).